FSHB (follicle stimulating hormone subunit beta)
Description:
Together with the alpha chain CGA constitutes follitropin, the follicle-stimulating hormone, and provides its biological specificity to the hormone heterodimer. Binds FSHR, a G protein-coupled receptor, on target cells to activate downstream signaling pathways. Follitropin is involved in follicle development and spermatogenesis in reproductive organs.
Synonyms: HH24
Tractability: Small molecule: a structure with a bound ligand is known. Antibody: UniProt places it where antibodies can reach, with high confidence; its Gene Ontology location is reachable by antibodies, with high confidence; UniProt predicts a signal peptide or a membrane-spanning region.
Gene: Protein-coding gene on chromosome 11 (30,231,014 to 30,235,261, forward strand). Ensembl gene ENSG00000131808.
Subcellular location: Secreted
Pathways (Reactome):
Signal Transduction: G alpha (s) signalling events; Hormone ligand-binding receptors
Metabolism of proteins: Glycoprotein hormones
Gene Ontology:
Molecular function: follicle-stimulating hormone activity; protein binding; hormone activity
Biological process: G protein-coupled receptor signaling pathway; positive regulation of steroid biosynthetic process; transforming growth factor beta receptor signaling pathway; female gamete generation; female pregnancy; follicle-stimulating hormone signaling pathway; MAPK cascade; ovarian follicle development; positive regulation of cell migration; positive regulation of cell population proliferation; positive regulation of transcription by RNA polymerase II; progesterone biosynthetic process; spermatogenesis; cell communication; insulin secretion involved in cellular response to glucose stimulus; signaling
Cellular component: cytoplasm; extracellular region; follicle-stimulating hormone complex; receptor complex
Genetic constraint (gnomAD): Loss-of-function variants: 7 observed, 11.3 expected, observed/expected ratio (o/e) 0.62, 90% interval 0.35 to 1.16. The upper end of that interval is the gene's LOEUF score, 1.16, which puts it in group 5 of 6, group 1 being the genes least tolerant of losing a copy. Missense variants: 145 observed, 157.94 expected, observed/expected ratio (o/e) 0.92, 90% interval 0.8 to 1.05. Synonymous variants: 53 observed, 54.67 expected, observed/expected ratio (o/e) 0.97, 90% interval 0.78 to 1.22.
Homologues: Orthologues: chimpanzee FSHB (98% identical), macaque FSHB (96% identical), pig FSHB (93% identical), rabbit FSHB (92% identical), guinea pig FSHB (88% identical), mouse Fshb (86% identical), rat Fshb (83% identical), dog FSHB (79% identical), tropical clawed frog fshb (56% identical), Drosophila melanogaster Gpb5 (19% identical). Paralogues in human: TSHB (38% identical), LHB (35% identical), CGB3 (33% identical), CGB5 (33% identical), CGB7 (33% identical), CGB8 (33% identical), CGB1 (32% identical), CGB2 (32% identical), GPHB5 (28% identical).
Diseases named in the same sentence as FSHB in open-access papers:
FSHB is named in the same sentence as 51 diseases in open-access papers, as found by Europe PMC text mining. Sharing a sentence is not in itself a finding about the gene and the disease. The quoted sentences say what the papers report.
endometriosis (29 papers, 2016 to 2025). The growth of functional endometrial tissue in anatomic sites outside the uterine body. "It has been shown that polymorphisms in the FSHB gene play a role in the pathogenesis of endometriosis." (PMID 40450304, 2025). "A potential common genetic factor is the top locus of the DZT GWAMA, FSHB as this locus has also been associated with endometriosis, PCOS, ovarian cyst, and menorrhagia, and the direction of effect differs between traits." (PMID 40423937, 2025). "We performed a case-control study, aiming to investigate the possible relationship between the FSHB rs10835638 variant and the development and/or progression of endometriosis in 326 women with endometriosis and 482 controls." (PMID 37909652, 2023). "Alternate alleles of SNPs in strong LD upstream of FSHB are alternatively associated with endometriosis and PCOS: i.e. one haplotype confers risk to endometriosis, the other to PCOS." (PMID 38049874, 2023). "There is substantial pleiotropy in loci implicated in gynaecological characteristics, for instance genetic variants in high linkage disequilibrium (LD) in the FSHB locus are linked to 11 traits, including endometriosis." (PMID 37159502, 2023). "Our results suggest that the FSHB rs10835638 variant is associated with the development of minimal/mild endometriosis in Brazilian women." (PMID 37909652, 2023). "FSH-lowering, and LH- and testosterone-heightening polymorphisms of the FSHB promoter (allelic variants A rs11031002 and C rs11031005) exhibit a protective effect for endometriosis (OR = 0.60–0.68)." (PMID 36430184, 2022). "Previously, we reported the SNP (rs11031010, rs1782507, rs555621) association in the same region as the FSHB gene (8–16 Kb upstream) and in the same cohorts of woman with endometriosis, uterine leiomyoma, endometrial hyperplasia and BMI (rs555621)." (PMID 36430184, 2022). "Other studies also reported the association of the FSHB promoter polymorphisms with endometriosis (rs74485684), menarcheal age (rs11031010, rs1782507, rs555621), PCOS and LH level in patients (rs11031010), and menopause age (rs12294104)." (PMID 36430184, 2022). "Given the importance of FSH in regulating production of oestrogens by the ovarian granulosa cells, the finding of SNPs associated with the FSHB gene provides a further link between endometriosis risk and oestrogen action(s)." (PMID 35514537, 2022). "In conclusion, the findings of the present study suggest that, when examined individually, the presence of the variant T allele in the FSHB:c.-211G>T SNV affected LH levels in women with overall endometriosis and minimal/mild disease." (PMID 34659133, 2021). "Of the genome-wide significant endometriosis risk genes in the most recent GWAS, FSHB emerges as one of special interest because this gene regulates central aspects of female reproduction." (PMID 33854783, 2021). "Recently, our group studied the effect of FSHB:c.-211G>T SNV on the reproductive outcomes in 140 Brazilian women with infertility mainly caused by males or tuboperitoneal abnormalities (except endometriosis)." (PMID 34659133, 2021). "The FSHB genetic risk factor for endometriosis involves a large (∼130kb) haplotype with two common alleles at frequencies of about 85 and 15% in European populations." (PMID 33854783, 2021). "Characteristics of women with endometriosis according to dominant model of the FSHB:c.-211G>T variant." (PMID 34659133, 2021). "In particular, a recent study investigated in a Greek population three of these SNPs: rs7521902, rs10859871 and rs11031006, mapped respectively on WNT4, VEZT and FSHB genes, highlighting a significant association with endometriosis." (PMID 32143537, 2020). "The recent meta-analysis of 11 GWAS determined the region on chromosome 11 (11p14.1, rs74485684) harboring the FSHB gene as that associated with endometriosis." (PMID 33552117, 2020).
endometriosis (continued). "Recently, some evidence for an association between endometriosis and SNPs of FSHB was reported in independent targets from the UK Biobank, firmly supporting this result." (PMID 32143537, 2020). "The choice of which polymorphisms were to be analysed fell to WNT4, VEZT and FSHB genes because of their hypothetical correlation with endometriosis, according to recent findings in the literature." (PMID 32143537, 2020). "Our study provides evidence that a likely functional variant in the FSHB promoter is strongly associated with longer menstrual cycles, and to a lesser extent with female infertility and lower risk of endometriosis." (PMID 26732621, 2016). "CD109, SAA1, SAA2, FSHB, and SEZ6L2 are weakly associated with endometriosis, with higher levels of FSHB and SEZ6L2 correlating with an increased risk of endometriosis, and higher levels of CD109, SAA1, and SAA2 correlating with a decreased risk of endometriosis (PFDR < 0.05, PPH4 < 0.6)." (PMID 40450304, 2025). "Also, two SNPs (rs11031005; rs11031006) in this region of FSHB demonstrated statistically substantial pleiotropic associations mediating endometriosis and related features (age of menarche and menopause, and duration of the menstrual cycle)." (PMID 41373783, 2025). "Active TSSs in ESCs in the FSHB endometriosis risk locus were also identified." (PMID 37443771, 2023). "FSH subunit beta (FSHB), encoding the beta subunit of a pituitary glycoprotein that indices gamete production, was associated with endometriosis, uterine fibroids and migraine, and previous studies also link it to reproductive lifespan, menstrual cycle characteristics, FSH concentrations, and PCOS." (PMID 37159502, 2023). "The follicle-stimulating hormone subunit beta gene rs10835638 variant (c.-211G>T) may have detrimental effects on fertility and protective effects against endometriosis." (PMID 37909652, 2023). "Surprisingly, three SNPs that are 25–40 Kb upstream the follicle-stimulating hormone beta subunit (FSHB) gene promoter (namely rs11031002, rs11031005 and rs11031006) appeared to be pleiotropically associated with endometriosis and four different female reproductive traits." (PMID 33401535, 2021). "The T allele of the FSHB promoter polymorphism (rs10835638; c.-211G>T) results in longer menstrual cycles and later menopause and, while having detrimental effects on fertility, is protective against endometriosis." (PMID 26732621, 2016). "Additionally, we also found evidence which suggests that haplotype variants of the FSHB subunit might be implicated in the development of endometriosis." (PMID 36430184, 2022). "It should be noted that in previous studies only some of these polymorphic loci of the FSHB promoter (rs11031002 and rs11031005) and strongly linked SNPs (rs74485684, rs11031010r, s10835638, rs1782507, rs555621) have had demonstrated associations with endometriosis." (PMID 36430184, 2022). "Thus, the currently available literature data and the results of our study indicate the presence of FSH-lowering, and LH- and testosterone-heightening, due to the FSHB promoter loci (alleles A rs11031002 and C rs11031005) that is strongly associated with low risk of endometriosis." (PMID 36430184, 2022). "In addition to endometriosis, the 11p14.1 locus comprising FSHB has been associated with several female hormone-related traits including age at menarche and menopause, short menstrual cycle, polycystic ovarian syndrome, and increased risk of dizygotic twinning." (PMID 32121467, 2020). "Meanwhile, our study suggested that higher levels of EPHB4, RSPO3, FSHB, and SEZ6L2 were associated with an increased risk of endometriosis, while lower levels of CD109, SAA1, and SAA2 were also associated with an increased risk of endometriosis." (PMID 40450304, 2025).
endometriosis (continued). "The region upstream of the promoter of FSHB (follicle-stimulating hormone subunit B), regulating FSH (follicle-stimulating hormone) concentrations, has been associated with risk of endometriosis and several other gynaecological traits and diseases." (PMID 37443771, 2023). "A meta-analysis reported that genes associated with endometriosis that were involved in hormone signalling (WNT4/CDC42, GREB1, ESR1, FSHB) were also associated with diagnosis of fibroids." (PMID 35514537, 2022). "Numerous associative studies, including GWAS, have shown the relationship between endometriosis and polymorphism of sex hormone genes (FN1, FSHB, ESR1, CCDC170, LHCGR, SYNE1, etc.)." (PMID 36430184, 2022). "We observed independent protective effects (OR = 0.64–0.68) for endometriosis of the two SNPs located in the FSHB chain promoter (rs11031002 T>A and rs11031005 T>C) and an increased disease-risk effect TT haplotype caused by these loci (OR = 2.03)." (PMID 36430184, 2022). "This FSHB haplotype thus represents a remarkable example of a specific genetic factor with opposite effects on endometriosis and PCOS risks and their major features." (PMID 33854783, 2021). "Analysis of the interaction model between the FSHB:c.-211G>T, FSHR:c.919G>A and FSHR:c.2039G>A variants in women with endometriosis, according to the MB-MDR model." (PMID 34659133, 2021). "Variants of the FSHB and FSHR genes separately interfered with the hormonal profiles and IVF outcomes of women with endometriosis." (PMID 34659133, 2021). "In this study, we aimed to evaluate the effects of FSHB:c.-211G>T, FSHR:c.919G>A, and FSHR:c.2039G>A variants, alone and combined, on the hormonal profile and reproduction outcomes of women with endometriosis." (PMID 34659133, 2021). "The T allele of the FSHB:c.-211G>T SNV was associated with higher serum LH levels in women with overall and minimal/mild endometriosis." (PMID 34659133, 2021). "In relation to FSHB:c.-211G>T SNV (rs10835638), women carrying the T allele had significantly higher serum LH levels in overall (p=0.025) and minimal/mild endometriosis (p=0.036) in the dominant model (respectively)." (PMID 34659133, 2021). "Inspired by these findings, we aimed to evaluate the effects of FSHB:c.-211G>T, FSHR:c.919G>A, and FSHR:c.2039G>A variants, alone and combined, on the hormonal profile and reproduction outcomes of women with endometriosis." (PMID 34659133, 2021). "The rs74485684 SNP is located on chromosome 11p14.1 near FSHB gene, a locus significantly enriched for both endometriosis and migraine in our meta-analysis." (PMID 32121467, 2020). "In this study, we specifically wanted to test the association between rs11031006 (FSHB), rs10859871 (VEZT) and rs7521902 (gene polymorphisms) and greater susceptibility to the development of endometriosis in a native Sardinian population." (PMID 32143537, 2020). "Keywords included: endometriosis combined with genes, genetics, SNPs, genome-wide association study (GWAS), WNT4, VEZT, FSHB, next-generation sequencing (NGS) and epigenetics." (PMID 32143537, 2020). "Our UL GWAS meta-analysis indicates that genes previously associated with endometriosis and involved in hormone-signaling pathways are also associated with UL (WNT4/CDC42, GREB1, ESR1, and FSHB)." (PMID 31649266, 2019). "We found that the druggable genes EPHB4, CD109, SAA1, SAA2, FSHB, and SEZ6L2 may be associated with the pathogenesis of endometriosis and are potential therapeutic targets for drug treatment." (PMID 40450304, 2025). "This study indicates that the druggable genes EPHB4, CD109, SAA1, SAA2, FSHB, and SEZ6L2 may be associated with the pathogenesis of endometriosis and are potential therapeutic targets for drug treatment." (PMID 40450304, 2025). "The genotypes and allelic frequencies of the FSHB variant were not different between women with and without endometriosis, even when the group was subdivided into fertile and infertile." (PMID 37909652, 2023).
endometriosis (continued). "FSHB:c.-211G>T affected LH levels in women with overall endometriosis and minimal/mild disease." (PMID 34659133, 2021). "The genotype frequencies of the FSHB and FSHR variants in Brazilian women with endometriosis." (PMID 34659133, 2021). "Finally, we confirm the importance of the FSHB upstream region on different female menstrual traits and reproductive outcomes, including endometriosis disease." (PMID 33401535, 2021). "Five additional new loci significantly associated with the risk of endometriosis (p < 5 × 10−8) of genes involved in sexual steroid hormone pathways (FN1, CCDC170, ESR1, SYNE1 and FSHB) were identified, for a total of 16 genomic regions associated with endometriosis risk in one or more populations." (PMID 32143537, 2020). "In addition to replicating previously reported loci, we identify five novel loci significantly associated with endometriosis risk (P<5 × 10−8), implicating genes involved in sex steroid hormone pathways (FN1, CCDC170, ESR1, SYNE1 and FSHB)." (PMID 28537267, 2017). "We conducted a GWA meta-analysis of ∼7 million SNPs in 17,045 endometriosis cases and 191,596 controls, confirmed 9 out of 11 previously reported European risk loci, and identified five new genomic regions in or near CCDC170, SYNE1, FSHB, FN1 and 7p12.3 harbouring endometriosis risk loci." (PMID 28537267, 2017). "The authors concluded that FSH levels, genetically regulated by SNPs located upstream of the FSHB promoter, can influence a number of menstrual cycle traits such as length and menopause timing, but also reproductive outcomes, including infertility and endometriosis." (PMID 33401535, 2021). "In addition to replicating 9 of the 11 previously reported European risk loci, this GWA meta-analysis identified 5 novel loci significantly associated with endometriosis risk (P<5 × 10−8), implicating genes involved in sex steroid hormone pathways (FN1, CCDC170, ESR1, SYNE1 and FSHB)." (PMID 28537267, 2017). "Therefore, the association of the FSHB polymorphism with infertility appears to be independent of the association with endometriosis." (PMID 26732621, 2016). "CD109, SAA1, SAA2, FSHB, and SEZ6L2 are considered to provide low-level evidence of colocalization with endometriosis (PPH4 ≤ 0.6)." (PMID 40450304, 2025). "GWASs have also demonstrated a genetic overlap between UL and breast cancer, particularly in the ER+ subtype, as well as with endometriosis, involving genes such as WNT4/CDC42, GREB1, ESR1, and follicle-stimulating hormone subunit beta (FSHB)." (PMID 38790186, 2024). "Similarly, genes shared between endometriosis, uterine fibroids, ovarian cancer, migraine and depression (RHOA, FOXP1, ESR1, WNT4, GREB1, FSHB), and endometriosis, migraine and asthma (IGF1, SMAD3, MFHAS1), were enriched in hormone receptor signalling and inflammation pathways, respectively." (PMID 37159502, 2023).